JAG1 (jagged canonical Notch ligand 1)
Diseases named in the same sentence as JAG1 in open-access papers (continued):
Sharing a sentence is not in itself a finding about the gene and the disease.
tumor (continued). "To investigate the correlation between JAG1 and tumor aggressiveness, we verified the expression of JAG1 in orthotopic xenografts derived from the GBM cell lines (LN229 and U87MG)." (PMID 38092725, 2023). "Cancer cells have been observed to induce expression of Jag1/2 in MDSCs via the NF-Kβ pathway and targeting Jag1/2 in MDSCs by use of a neutralizing antibody was shown to inhibit arginase I, iNOS and decreased tumor growth." (PMID 38269089, 2023). "Thirdly, we elucidated the interrelationship between laminin, integrin, TRB3/JAG1, and Notch, which offered novel insight for tumor signaling pathways investigations." (PMID 35585515, 2022). "JAG1, expressed in tumor cells, has been shown to activate Notch signaling in neighboring endothelial cells to promote angiogenesis." (PMID 35682974, 2022). "The high level of JAG1 was also correlated with higher tumor stage and grade, and poor prognosis and survival rate in lymph node-negative breast cancer." (PMID 36476410, 2022). "Regarding functional regulation, tumor-derived factors upregulate JAG1/2 on MDSCs through NFkB-p65 signaling, forming a suppressive immune microenvironment." (PMID 35332121, 2022). "Analysis of JAG1 expression in human tumor samples from 154 men revealed that JAG1 is more highly expressed in metastatic PC than in localized PC or benign prostatic tissues." (PMID 36428807, 2022). "Pathway analyses and ligand/receptor status model cellular interactions among ICC/IDC and the tumor microenvironment (TME) including JAG1/NOTCH." (PMID 36229464, 2022). "Elevated JAG1 leads to abnormal up-regulation of its receptor Notch-1 accompanied by inhibition of tumor cell apoptosis, development and metastasis of tumors." (PMID 35642021, 2022). "In tumor models, JAG1 plays an important role in promoting sprouting angiogenesis and antagonizing DLL4-mediated Notch signaling 44-47." (PMID 35401837, 2022). "As one of the most active cell surface ligands in the Notch signaling pathway, Jagged canonical Notch ligand 1 (JAG1) is overexpressed in many cancer types with a close relationship to tumor biology." (PMID 36539520, 2022). "RT-qPCR results documented that lncRNA HOXA-AS2, KDM2A, and JAG1 expression was diminished, while that of miR-302a was augmented in tumor tissues of BALB/c mice silencing lncRNA HOXA-AS2." (PMID 35181676, 2022). "As one of the most studied factors in the Notch signaling pathway, JAG1 is known to function as tumor promoter in malignancies by inducing angiogenesis or immune cell infiltration." (PMID 35181676, 2022). "In this neoplasia, NOTCH3 promotes JAG1, a phenomena that is caused by a NOTCH3/JAG1 auto-sustaining loop." (PMID 35326610, 2022). "In paired OSCC samples, JAG1 mRNA levels were upregulated in tumor tissues compared to adjacent normal tissues (GSE37991)." (PMID 35249111, 2022). "SMAD-dependent TGF-β signaling induces JAG1 upregulation in the cancer cells and activates Notch 1 in osteoblasts within the niche which then secretes IL-6, stimulating the tumor growth and affecting osteoclast differentiation." (PMID 36605720, 2022). "Overexpression of JAG1 in endothelial cells increased the growth of subcutaneous Lewis lung carcinoma (LLC) tumour transplants." (PMID 34944837, 2021). "Cytoplasmic Notch and phosphorylated Akt (pAkt) correlate with nuclear NFκB in TNBC tumour samples, while mechanistic work in triple negative cell lines demonstrated JAG1-Notch1 (but RBPJκ-independent) stimulation of Akt via mTOR and IκB kinase (IKK) α." (PMID 34295896, 2021). "Circ_0084582 is considered to function as a tumor promoter in OS through modulating the JAG1 level via sponging miR-485-3p." (PMID 34421997, 2021). "The previous study also affirms that JAG1 is a pro-oncogene in OS, and miR-26a repressed tumor growth by targeting JAG1 in OS." (PMID 34421997, 2021).
tumor (continued). "Strikingly, while JAG and DLL ligands almost equally contribute to Notch signaling in the tumor, JAG1 is the main contributor to Notch signaling in lymph node cells, thus confirming once more the relevance of JAG ligands in metastasis." (PMID 34830900, 2021). "JAG1 expressed on endothelial cells in the tumour microenvironment activates Notch1 in adjacent BCSCs, resulting in ZEB1 induction and increased stemness." (PMID 34295896, 2021). "Lkb1 is mainly described as a tumor suppressor, whereas overall Jag1 is shown to be pro-tumorigenic here." (PMID 33268505, 2021). "The Notch ligands DLL4 and Jag1 are the best characterized Notch pathway factors that have roles in tumor angiogenesis." (PMID 33681228, 2021). "JAG1 is a cell surface ligand that primarily acts through the highly conserved Notch signal pathway, which influences tumor development." (PMID 33795521, 2021). "In primary TNBC samples high ZEB1 expression was correlated with upregulated JAG1 and Notch activity in invasive tumour regions." (PMID 34295896, 2021). "Deletion of Jag1 accelerated ADM/PanIN in KJC mice, suggesting a tumor-suppressive role of Jag1 in the early stage of tumorigenesis." (PMID 33268505, 2021). "Mechanistically, Jag1 regulates expression of Lkb1, a tumor suppressor involved in the development of pancreatic cystic neoplasm." (PMID 33268505, 2021). "Next, we evaluated the roles of both Jag1 and Jag2 in CSC induction by inhibiting Notch signaling with Jag1 and Jag2 blocking antibodies in the tumor cell-macrophage co-culture assay." (PMID 34911937, 2021). "Among the genes above, JAG1 is widely reported to augment angiogenesis and tumor growth in animal model." (PMID 34667158, 2021). "In HNSCC with overexpression of Jag1, xenografted together with human endothelial cells into mice, stimulated angiogenesis, and tumor invasion phenotypes." (PMID 33430387, 2021). "High levels of Notch1 correlates to higher numbers of tumor-associated macrophages (TAMs) in head and neck cancer and NOTCH1 and NOTCH2 induce a TAM-anti-inflammatory phenotype via JAG1." (PMID 32796631, 2020). "In vitro knock down of JAG1 in SUM149 human breast cancer cells significantly reduced their tumor organoid formation, confirming the role of Notch-Jagged signaling in tumor progression." (PMID 32426371, 2020). "While tumor-derived Jag1 facilitates bone metastasis, chemotherapy induces the expression of Jag1 in osteoblasts and further enhances tumor cell survival." (PMID 32092942, 2020). "In prostate cancer, upregulation of Jag1 correlates with the advanced metastatic stage of the tumor." (PMID 32796631, 2020). "Inhibition of Notch signalling by anti-JAG1/2 antibodies reduces the accumulation and tolerability of MDSCs in tumours, resulting in enhanced anti-tumour responses." (PMID 32778818, 2020). "TGF-β released from the destruction of bone matrix also creates a feedback loop to further activate Jag1 expression in tumor cells (termed the “Vicious Cycle”) and enhance the metastatic potential of the cancer." (PMID 32092942, 2020). "In the present study, we provide further evidence that endothelial cells within the tumor function as a CSC niche by directly providing Jag1 to the Notch1 receptors expressed in breast CSCs to elevate Zeb1 expression." (PMID 33046710, 2020). "In this study, they showed that Jag1 antibody (15D11) targeting both tumor- and osteoblast-derived Jag1 helps sensitize skeletal metastases to chemotherapy in osteoblastic gain of function Jag1 mouse model." (PMID 32092942, 2020). "Jag1 is highly expressed in circulating tumor cell clusters with higher metastatic potential and by cancer cells that resist to drugs." (PMID 32848867, 2020). "The DLL4 overexpression showed fewer but larger vessels whereas JAG1 upregulation produced more vessels in tumor cells." (PMID 32046779, 2020). "Second, aged myoepithelial cells display increased expression of Jag1 and Tgfβ, which can stimulate tumor proliferation and invasion." (PMID 33378681, 2020).
tumor (continued). "In breast cancer, tumor-derived Jag1 induces IL-6 secretion from osteoblasts, which feeds back to cancer cells to promote tumor growth." (PMID 32092942, 2020). "Tumor-bearing mice treated with inhibitory monomeric soluble JAG1 (sJAG1) showed a significant reduction in tumor burden concurrent with a decrease in splenic Treg cell numbers." (PMID 32922403, 2020). "Notch3 and Jag1, components of the Notch signaling pathway, were increased in expression and confirmed by protein expression analysis in the primary tumor and tumor cells." (PMID 32652895, 2020). "In particular, NOTCH/JAG1 signaling resulted in playing a fundamental role in MSC-dependent control of tumor initiation, growth, and chemoresistance." (PMID 31861268, 2019). "Conversely, interference with ligand specific signaling by monovalent soluble JAG1 or soluble DLL1 efficiently improved anti-tumor immunity or blocked anti-tumor and allogeneic T-cell responses, respectively." (PMID 30940183, 2019). "To further study the role of Notch3 and its ligand Jag1 in EC-tumor interaction, we silenced Jag1 expression on E4+ECs using siRNA and showed an inhibition of APOCC or OVCAR3 proliferation in co-cultures with E4+ECssiJag1." (PMID 31182109, 2019). "Systemic blockade of Jag1 and 2 with Jagged ligand-specific antibodies overcame tumor-induced T-cell tolerance, indicating the involvement of these ligands in T-cell suppression." (PMID 30940183, 2019). "EFEMP1 has also been reported to activate Notch signaling in vitro, although with less efficiency than JAG1, and to exert both tumor suppressive and oncogenic effects in various cancers by participating in multiple signaling pathways." (PMID 30102696, 2018). "Immunofluorescence (IF) analysis of endogenous LGR5 protein confirmed that this particular stem cell-like tumor population was reduced in the Jag1 KO mice (from 48 in the WT to 21% in average), whereas the ISC compartment of normal crypts remained unaffected." (PMID 30065304, 2018). "JAG1 is the ligand in the canonical Notch pathway in tumor growth through maintaining cancer stem cell populations, promoting cell survival, inhibiting apoptosis, and driving cell proliferation and metastasis." (PMID 29520031, 2018). "While we cannot exclude the effects of other cell-contact-mediated signalling pathways on chromatin structure, our data together demonstrate that JAG1-expressing tumour cells can repress SAHF formation in adjacent senescent cells in a JAG1-dependent manner." (PMID 29743479, 2018). "This led to a model for macrophage-enhanced iTEM in which NRG1 produced by tumor cells binds to ErbB3 on macrophages and induces expression of JAG1, which in turn enhances tumor cell intravasation." (PMID 29636067, 2018). "In the studies reported here, we identified a novel paracrine loop for intravasation, in which NRG1 production by tumor cells stimulates macrophages to produce JAG1, resulting in increased transendothelial migration." (PMID 29636067, 2018). "We found a dramatic upregulation of the canonical NOTCH1 target gene HEYL and a concurrent downregulation of HMGA1 and HMGA2 in fibroblasts co-cultured with JAG1-expressing tumour cells, particularly A549 and Hep3B cells." (PMID 29743479, 2018). "Taken as a whole, our data suggest that NRG1 in tumor cells, and ErbB3 and JAG1 in macrophages can play an important role in the metastatic cascade." (PMID 29636067, 2018). "The number of SAHF-positive red cells inversely correlated with the level of JAG1 expressed by the tumour cell lines." (PMID 29743479, 2018). "Stimulation of macrophages with NRG1 upregulated mRNA and protein expression of JAG1, a ligand of the Notch receptor, and JAG1 production by macrophages was important for transendothelial migration of tumor cells." (PMID 29636067, 2018). "They showed that SLUG facilitated E-cadherin repression (through Notch1 inhibition) and inhibition of HEYL blocked tumor growth and metastasis, showing JAG1-Notch1-SLUG dependency." (PMID 30515368, 2018).
tumor (continued). "Jag1 is reported as tumor promoting in many cancer types and on this basis, it is considered to be a target for anti-cancer agents." (PMID 30521558, 2018). "We found that intestinal-specific Jag1 deletion or antibody targeting Jag1 prevents tumor initiation in mice." (PMID 30065304, 2018). "We have found that intestinal epithelial Jag1 deletion prevents ApcMin/+ tumor formation, reduces expression of several ISC markers, and inhibits tumor spheroid growth and re-passaging, a measure of TIC activity." (PMID 30065304, 2018). "We show that NRG1 can stimulate the ErbB3 receptor on macrophages in order to induce JAG1 expression, which acts as a ligand for the tumor cell Notch receptor, increasing their capacity for transendothelial migration and intravasation." (PMID 29636067, 2018). "JAG1 induction has been reported to affect both tumor cells and multiple components of the neoplastic microenvironment, including the vasculature and immune cells." (PMID 30231940, 2018). "We propose a new mechanism by which tumor released-gal-3 increases angiogenesis by influencing JAG1/Notch signaling in endothelial cells." (PMID 28533486, 2017). "Our findings establish gal-3 as a molecular regulator of the JAG1/Notch-1 signaling pathway and have direct implications for the development of strategies aimed at controlling tumor angiogenesis." (PMID 28533486, 2017). "We concluded that DLL4 and JAG1 promote tumour growth by modulating tumour angiogenesis via different mechanisms." (PMID 28445154, 2017). "DLL4 is predominantly expressed in the ECs of tumour blood vessels but also in a small proportion of tumour cells; whereas JAG1, although also expressed in ECs, is more highly expressed in tumour cells and mural cells." (PMID 28445154, 2017). "Here, we investigated a new mechanism by which gal-3 affects tumor angiogenesis by altering the balance of JAG1 and DLL4 expression and function in ECs." (PMID 28533486, 2017). "In vivo, both mDLL4 and mJAG1 expressed in tumour cells increased endogenous JAG1 expression in tumour tissues of either SAS or PC3." (PMID 28445154, 2017). "Altogether, we propose a model to depict the role of DLL4 and JAG1 in tumour angiogenesis and growth." (PMID 28445154, 2017). "JAG1 on the other hand can signal to both tumour cells and ECs to promote angiogenesis and tumour growth via the MAPK pathway." (PMID 28445154, 2017). "Notch signalling is significantly increased by JAG1 in vitro and in vivo, especially in tumour stromal cells." (PMID 28445154, 2017). "Combined treatment with DBZ and bevacizumab dramatically reduced expression of endogenous JAG1 in both EV- and mDLL4-tumours (X-XI versus I-II)." (PMID 28445154, 2017). "JAG1-induced Notch signaling plays an important role in tumor biology affecting both proliferation and metastasis of tumor cells and also activating neighboring endothelial cells to promote neovascularization and growth of experimental tumors in mice." (PMID 28533486, 2017). "mDLL4 decreased vessel number but harboured bigger vessels with hDLL4 while JAG1 increased tumour vessel numbers only." (PMID 28445154, 2017). "Many studies have focused on the effects of endothelial DLL4 or JAG1 on tumour growth and vascularisation." (PMID 28445154, 2017). "Blocking DLL4 signalling using anti-DLL4 antibody effectively delayed tumour growth possibly by disrupting functional angiogenesis, implying that DLL4 is a dominant ligand over JAG1 in tumour angiogenesis and tumour growth." (PMID 28445154, 2017). "JAG1 was abundantly expressed in mJAG1-expressing tumours ratifying the transduction efficacy (III, VI, IX and XII)." (PMID 28445154, 2017). "In this study we found that gal-3 has an essential role in regulating the tumor growth of JAG1 expressing tumors." (PMID 28533486, 2017). "Overall we found that gal-3 increased the growth rate of JAG1-expressing tumors and the vascular lumen area while decreasing the tumor hypoxic areas." (PMID 28533486, 2017).
tumor (continued). "Taking into account all these results, we suggest that gal-3 positively regulates JAG1's biological role in inducing tumor growth, endothelial sprouts, blood vessel maturation and the formation of luminal structures." (PMID 28533486, 2017). "The Notch ligands JAG1 and Dll4 and the Notch receptors Notch1–4 are functionally overexpressed in KS tumor cells." (PMID 27760204, 2016). "In spite of these clinical observations, the molecular contribution and functionality of JAG1 in neoplastic diseases remain to be established." (PMID 26930648, 2016). "The Notch ligands JAG1 and Dll4, and the Notch receptors Notch1–4 are highly expressed in KS tumor cells." (PMID 27760204, 2016). "In particular, it is of high importance to unravel the molecular mechanisms whereby Jag1 is induced in this tumour type." (PMID 27918553, 2016). "In accordance with the immunohistochemical data, we found that Jag1 mRNA expression is significantly upregulated in ICC samples compared to respective non-tumour liver samples (P<0.0001)." (PMID 27918553, 2016). "In summary, this study is the first to demonstrate the effect of directly modulating endothelial Jag1 in tumor development." (PMID 26213336, 2015). "Notch ligands (JAG1-2, DLL1,4), like Notch receptors, showed higher mutations frequencies in tumor cell lines, although these were mainly restricted to the endometrium and prostate cell types." (PMID 25907971, 2015). "Collectively, our findings suggest a synergistic role for endothelial Jag1 and TGFβ in regulating tumor-stimulated mesenchymal phenotypes in ECsMes." (PMID 25623554, 2015). "This means that the effect of modulating endothelial Jag1 remained constant in time (evolution of tumor progression)." (PMID 26213336, 2015). "Our data confirmed that tumor-activated TGFβ/Smad1/5 phosphorylation was regulated by synergistic activation of notch and TGFβ pathway by showing that TGFβ and Jag1 were capable of inducing Smad5 phosphorylation as well as Hes1 up-regulation." (PMID 25623554, 2015). "A recent study of JAG1 expression by immunohistochemistry in pseudopalisading GBM tumor cells suggests that hypoxia can focally promote its expression in tumor cells surrounding necrotic regions, resulting in unequal ligand levels." (PMID 25557173, 2015). "Jagged-1 (Jag1) is a Notch ligand required for embryonic and retinal vascular development, which direct contribution to the regulation of tumor angiogenesis remains to be fully characterized." (PMID 26213336, 2015). "Endothelial specific Jag1 overexpression led to significantly accelerated growth of subcutaneous tumors, from day eleven after injection, with a final tumor volume more than two-fold larger (1370 mm3) than that of the respective controls (570 mm3)." (PMID 26213336, 2015). "A recent study showed that NOTCH2 and its ligand Jag1 are highly expressed in human HCC tumours, suggesting activation of NOTCH2 signalling in HCC45." (PMID 25985737, 2015). "The results presented here describe the effect of modulating endothelial Jag1 in tumor angiogenesis and metabolism and consequently in tumor development and progression." (PMID 26213336, 2015). "By modulating levels of endothelial Jag1, we observed that this ligand regulates tumor vessel density, branching, and perivascular maturation, thus affecting tumor vascular perfusion." (PMID 26213336, 2015). "Taken together, endothelial Jag1 over-expression led to the formation of a dense, mature, and more functional tumor vascular plexus, that contributes to increased tumor growth and progression." (PMID 26213336, 2015). "We have shown that EC effect on cancer development is strongly dependent on direct cell-to-cell contact and is regulated through endothelial Jag1/tumor notch activation." (PMID 25380486, 2014).